INS (insulin)
Diseases named in the same sentence as INS in open-access papers (continued):
Sharing a sentence is not in itself a finding about the gene and the disease.
Hyperglycemia (continued). "Fucoidan has also been implicated in inhibiting dipeptidyl peptidase IV, an enzyme responsible for the rapid degradation of incretin hormones which are known to prevent hyperglycaemia and increase insulin production." (PMID 33440853, 2021). "As a result, MET is believed to be a reliable and efficacious medicine to treat type 2 DM, as well as to protect the remaining ß-cells from further insulin release induced by hyperglycemia." (PMID 34527070, 2021). "The postoperative hyperglycemic response was associated with significantly elevated serum levels of insulin and C-peptide, indicating the development of insulin-resistant hyperglycemia." (PMID 33526980, 2021). "Class-1 PI3Ks are critical targets in cancer therapy, but compound inhibition of all PI3K isoforms causes liver damage, hyperglycaemia, and hyperinsulinaemia as a result of the central role of PI3K in insulin signalling." (PMID 34704005, 2021). "Cyanidin-3-glucoside, the main anthocyanin compound of black rice, suppresses the occurrence of high-fat-diet-induced obesity, increases hyperglycemia and insulin sensitivity via AMP-activated protein kinase in type 2 diabetic mice." (PMID 34917106, 2021). "Reducing hyperglycemia and enhancing insulin sensitivity are priorities for the successful treatment of these patients." (PMID 34575946, 2021). "It is a systemic and progressive disease characterized by hyperglycemia arising, at least in part, from beta cell dysfunction and peripheral insulin resistance." (PMID 33566837, 2021). "This IWCS is demonstrated to accurately monitor glucose fluctuations, and responsively deliver insulin to regulate hyperglycemia in diabetic rat model." (PMID 34081407, 2021). "Islet amyloid polypeptide (IAPP, amylin) is secreted from pancreatic β-cells together with insulin, and along with hyperglycemia its expression increases, leading to extracellular deposition and damage to pancreatic β-cells." (PMID 33918379, 2021). "Twenty-five percent (18/73) required insulin for idiopathic hyperglycemia of prematurity and were smaller in weight and head circumference at discharge." (PMID 34447729, 2021). "There are several medical approaches for postprandial hyperglycemia, including stimulating insulin secretion, improving insulin sensitivity to increase glucose uptake by muscle and adipose tissue, and inhibiting glucose reabsorption in the kidney." (PMID 35008753, 2021). "This profound increase in free fatty acid and ketone concentrations lead to a further increase in the magnitude of hyperglycemia by inducing insulin resistance and ultimately results in ketonemia and metabolic acidosis." (PMID 36994324, 2021). "In streptozotocin-induced hyperglycemic mice model, we demonstrated that PGLP-1-VP can act as a GLP-1R agonist to improve hyperglycemia and increase insulin sensitivity." (PMID 33574570, 2021). "The aspartame-exposed groups consumed fewer net calories but were found to have fasting hyperglycemia and impaired insulin tolerance." (PMID 33868167, 2021). "Together, these results indicate that chronic imeglimin treatment improves glucose tolerance and amplifies glucose‐stimulated insulin secretion in this extreme male ZDF rat model of T2D with marked hyperglycaemia (20.1 mmol/L)." (PMID 33855202, 2021). "As the liver plays a central role in glucose metabolism by maintaining a balance between its uptake and storage, hepatic insulin resistance is thought to be largely responsible for the development of fasting hyperglycaemia." (PMID 34639123, 2021). "Reducing ER stress is sufficient to normalize phenotypes including hyperglycemia and insulin sensitivity by improving insulin action at the liver." (PMID 34445033, 2021). "To further support the essential role of insulin‐dependent cascades in heparin‐induced hyperglycaemia, we tested the role of GLUT4 upstream PI3K/Akt signalling." (PMID 34277977, 2021).
Hyperglycemia (continued). "More and more evidence shows that AGEs can cause mitochondrial dysfunction of pancreatic islets, resulting in excessive superoxide production, reduced ATP level, and ultimately insulin secretion dysfunction, leading to continuous hyperglycemia in the body." (PMID 35370932, 2021). "On the other hand, systemic proinflammation in the context of hyperglycemia, insulin resistance, oxidative stress and activation of the renin angiotensin system are systemic disturbances in obese individuals that contribute independently and synergistically." (PMID 34746259, 2021). "Several studies demonstrated the existence of an adipoinsular axis, characterized by leptin-inhibited insulin synthesis and secretion, promoting hyperglycemia, as shown in our model." (PMID 34578791, 2021). "In accordance with the well-established link between abnormal fat deposition and glucose dysregulation, our high-5HT animals exhibit hyperglycemia and impaired glucose tolerance and insulin sensitivity, both of which progress with aging." (PMID 34065591, 2021). "Long-term exposure to elevated circulating FFA inhibits insulin signaling in the muscle, contributes to hyperglycemia in the liver, and decreases insulin secretion in the pancreas." (PMID 33819181, 2021). "Sasaki R., Nishimura N., Hoshino H., Isa Y., Kadowaki M., Ichi T.,Horio F. Cyanidin 3-glucoside ameliorates hyperglycemia and insulin sensitivity due to downregulation of retinol binding protein 4 expression in diabetic mice." (PMID 34901716, 2021). "GLP-1 and GIP are able to stimulate insulin secretion and inhibit glucagon release, lowering the post-prandial hyperglycemia." (PMID 34205680, 2021). "This type of hypercaloric food promotes hyperglycemia and insulin secretion that induce fat accumulation in adipose tissue." (PMID 33921979, 2021). "In particular, T1DM is a condition caused by autoimmune-induced pancreatic beta cells destruction, leading to absolute deficiency of insulin, while in T2DM, hyperglycaemia is a consequence of insulin-resistance." (PMID 34210044, 2021). "When hyperglycemia occurs despite normal insulin production, this is typically characterized as type 2 diabetes (T2D)." (PMID 34564296, 2021). "Our inpatient hyperglycemia insulin protocol recommends a well-standardized 50% basal (glargine)-50% bolus (lispro) therapy." (PMID 34529703, 2021). "Individuals with T2DM who follow this pattern show a significant reduction in postprandial hyperglycemia, whereas insulin-resistant individuals show significant improvements in insulin sensitivity and, interestingly, a reduction in hunger." (PMID 34201382, 2021). "Altogether, these data suggest that GDM primes the placenta to overstimulate the insulin signaling to compensate sustained exposure to hyperglycemia." (PMID 34360849, 2021). "Hasan described a 15 years old boy from consanguineous parents and positive family history for DM, who developed insulin treated hyperglycemia at the age of 9 years, with adequate metabolic control." (PMID 34831749, 2021). "Postprandial hyperglycemia encourages the pancreas to secrete insulin, and an increase in plasma insulin concentration triggers the uptake and use of glucose by skeletal muscle." (PMID 34203830, 2021). "Selection bias likely occurred, leading to treat more frequently women with a more pronounced hyperglycemia and/or with already large babies, as suggested by the higher rate of macrosomia in offspring born to insulin-treated mothers in one study." (PMID 35069449, 2021). "It has been proposed that maternal hyperglycemia leads to excess fetal insulin that alters the expression of hypothalamic neurotransmitters and leads to childhood hyperphagia and overweight." (PMID 33407256, 2021). "Presently, treatment of T2DM is indirect and piecemeal, with use of metformin, insulin secretagogues and glucosurics to diminish hyperglycemia; and various agents to treat MetS features of hyperlipidemia and hypertension." (PMID 34766133, 2021).
Hyperglycemia (continued). "Islet transplantation has proven to be successful in controlling hyperglycemia and providing insulin-independence for many diabetic patients." (PMID 34589059, 2021). "Previously, DM1 was considered a chronic and single autoimmune disease, classically characterized by a deficiency in insulin production due to a T-cell mediated attack on insulin-producing pancreatic β-cells, which resulted in hyperglycemia." (PMID 35048037, 2021). "Transport of insulin out of a macroencapsulation device is a critical design parameter, as insufficient diffusion of insulin into the blood in response to hyperglycemia is a failure of the device to adequately treat T1D." (PMID 34155834, 2021). "For instance, Thiazolidinedlones (TZDs), such as pioglitazone and rosiglitazone, are PPARγ agonists used as anti-diabetic drugs, that induce a decrease in plasma free fatty acid concentration and fasting hyperglycemia through an insulin-reducing effect." (PMID 34489627, 2021). "By the age of 16 months, 90% of saline-treated Wfs1 KO animals had developed hyperglycemia and needed supportive insulin administration." (PMID 34831417, 2021). "Elevated GH can contribute to hyperglycemia through multiple mechanisms, including decreased insulin-stimulated glucose uptake, increased endogenous glucose production, and altered glycogen synthesis." (PMID 34684381, 2021). "Implant of these stem cell‐derived pancreatic progenitors and immature hormone‐producing cells into immunodeficient mice produced grafts with mature insulin‐producing beta cells that protected the mice against chemically induced hyperglycemia." (PMID 34387389, 2021). "If drops in insulin needs are indeed considerable and expose patients to bouts of hyperglycaemia, then the therapy’s safety is undermined." (PMID 33099763, 2021). "Intranasal insulin, one such form, has a rapid mode of action while effectively controlling postprandial hyperglycemia." (PMID 34540446, 2021). "Due to impaired insulin secretion and excessive glucagon secretion in T2DM patients, the glucagon/insulin ratio is abnormally increased, thus exacerbating the hyperglycemia." (PMID 34457002, 2021). "To investigate this further, we evaluated the effects of insulin treatment in NASH diet-fed hamsters with streptozotocin (STZ) -induced hyperglycemia." (PMID 33596938, 2021). "Sustained high blood glucose levels known as hyperglycemia (HG) and alterations in insulin secretion, e.g., hyperinsulinemia (HI), characterize T2D." (PMID 34203572, 2021). "In rodent models, significant fasting hyperinsulinemia was presented around 3–4 days of HFD prior to hyperglycemia or insulin resistance." (PMID 33817571, 2021). "Stress hyperglycemia is a normal homeostatic response to acute stress, which is characterized by increased glycogenolysis and gluconeogenesis along with insulin resistance." (PMID 33981655, 2021). "This further supports the therapeutic potential of IHZ in maintaining the glucose homeostasis and insulin sensitivity in HF induced hyperglycemia." (PMID 34155273, 2021). "The rationale is to provide stable background insulin concentration and to avoid reoccurrence of hyperglycemia during the transition time to SC insulin." (PMID 33945208, 2021). "Within T2DM, hyperglycaemia takes place due to the impaired insulin secretion through a dysfunction of the pancreatic β-cells and insulin malfunction." (PMID 34180336, 2021). "Evidence demonstrated that the introduction of amino acids within 4 h after birth diminished insulin-treated hyperglycemia incidence in preterm infants." (PMID 34736488, 2021). "Through destroyed β-cells of the pancreas, insulin release was inhibited by alloxan, leading to hyperglycemia." (PMID 34880923, 2021). "Dosage up- and down-titration had to be done with the glimepiride and metformin combination as well as insulin to control hyperglycemia, hypoglycemia, and glycemic variability." (PMID 33665047, 2021).
Hyperglycemia (continued). "The results revealed that the silencing of miR-107 and miR-103, which are elevated in the livers of obese/diabetic mice and humans, markedly enhanced hyperglycemia by facilitating insulin sensitivity in the adipose tissue and liver." (PMID 34069422, 2021). "The insulin–insulin receptor axis has proven to be crucial for glucose metabolism homeostasis and in critical conditions such as burn trauma, where stress hyperglycemia initially plays a redeeming role." (PMID 34575946, 2021). "Other features of NAFLD include hyperglycemia 2-h after glucose loading, even when the fasting blood glucose levels are normal, and hyperinsulinemia with decreased hepatic insulin clearance (confirmed with a large patient cohort)." (PMID 33441894, 2021). "First and foremost, it must be noted that ER stress contributes to insulin dysfunction, which leads to an enhanced progression of hyperglycemia in the blood vessels." (PMID 33995826, 2021). "Inhibition of P300 acetyltransferase activity by chemical inhibitors improved insulin signaling and alleviated hyperglycemia in obese mice." (PMID 33672754, 2021). "Approximately 50% of organ donors develop hyperglycaemia in intensive care, which is managed with insulin therapy." (PMID 33665687, 2021). "Pregnant women who develop GDM are thought to have decreased peripheral insulin sensitivity already present before pregnancy and dysfunctional β-cells unable to balance the increased insulin requirements, resulting in hyperglycemia." (PMID 34206854, 2021). "There were nodifferences between these options in the number of patients achieving the target, but morepatients being treated with multiple injections of insulin experienced hyperglycemia." (PMID 35111536, 2021). "Adipose tissue, skeletal muscles, and the liver manifest insulin resistance with insufficient cellular glucose uptake, which further accentuates and maintains the hyperglycemia." (PMID 34068151, 2021). "Studies have shown that hyperglycemia can increase the secretion of urinary calcium, uric acid, phosphorus, and oxalate, and insulin resistance can lead to a decrease in urine ammonium and PH value, both of which contribute to stone formation." (PMID 34834506, 2021). "Hyperglycaemia itself impairs the capacity of the pancreatic islet cells to secrete insulin, initiating a vicious circle in which the increase in insulin resistance causes a further increase in blood glucose levels." (PMID 34829645, 2021). "It is necessary to clarify not only the different types of fat in the diets, but also the lipid composition in the different organs and its relationship with the inflammatory environment and insulin sensitivity, as well as with hyperglycemia." (PMID 34440853, 2021). "Insulin treatment should be initiated if glucose level remains above 180 mg/dL for persistent hyperglycemia." (PMID 33808901, 2021). "Under a standard insulin regimen, hyperglycemia was rapidly corrected but marked hyperlactatemia occurred." (PMID 34419042, 2021). "Asparaginase-induced hyperglycemia can be explained by the fact that asparaginase decreases insulin production and insulin-receptor expression." (PMID 34640436, 2021). "The effect of SSTR2a on insulin secretion during hyperglycemia has been studied in SSTR2-knockout mice and in isolated cells but revealed only weak effects on insulin secretion." (PMID 33434183, 2021). "Using these estimations, T1DM patients are able to adjust insulin and carbohydrate intakes and prevent hypoglycemia and hyperglycemia episodes." (PMID 34450712, 2021). "Despite equivalent damage to the Islets of Langerhans following STZ treatment, Olfr1393 KO mice have a significant improvement in hyperglycemia and glucose tolerance, and can maintain lower blood glucose levels following administration of exogenous insulin." (PMID 34877823, 2021). "The tendency towards subclinical hyperglycemia in women with a history of GDM was accompanied by decreased insulin sensitivity." (PMID 34682918, 2021).
Hyperglycemia (continued). "Nonobese diabetic (NOD) mice were used, along with μCT, histomorphometry, histology, Raman spectroscopy, and RNAseq analyses of several skeletal sites in response to naturally occurring hyperglycemia and insulin treatment." (PMID 33977201, 2021). "The skeletal muscle is the most prominent consumer of circulating glucose, and any decrease in the insulin sensitivity of the skeletal muscle determines hyperglycemia and accentuates the hypercatabolic state of a severely burned patient." (PMID 34575946, 2021). "AGEs can cause islet mitochondrial dysfunction, resulting in excessive superoxide production and reduced ATP level, and eventually lead to insulin secretion dysfunction, leaving the body in a state of continuous hyperglycemia." (PMID 35370932, 2021). "Accurate carbohydrate counting is an essential skill for determining mealtime insulin boluses, however, its impact on improving glycaemic outcomes and reducing post-prandial hyperglycaemia have been modest." (PMID 34836409, 2021). "A 40% increase in plasma insulin levels under modest hyperglycemia was achieved in 15 healthy subjects who received a single oral dose of BBR in the hyperglycemic clamp study." (PMID 34556670, 2021). "Although insulin administration is very efficacious in the management of hyperglycemia, it requires carbohydrate counting with each meal to match insulin administration to the carbohydrate intake to achieve glycemic control." (PMID 34684381, 2021). "In most patients, different kinds of neuropathies come together, and are mainly a result of the long-lasting hyperglycemia, with created changes in insulin signalling as a key." (PMID 34943248, 2021). "In order to manage and subsequently minimize complications induced by hyperglycemia (i.e., diabetic retinopathy), the animals in need received insulin from 11.5 months of age." (PMID 34831417, 2021). "Insulin resistance is accompanied by hyperglycaemia and hyperlipidaemia and increased insulin secretion to maintain normal glucose levels." (PMID 34638652, 2021). "The hyperglycemia that occurs in T2DM is mainly caused by islet damage and insulin resistance in peripheral tissues." (PMID 34722505, 2021). "Although the animals that had free access to chow and water before cecectomy also developed hyperglycaemia, the serum levels of insulin and C-peptide were significantly reduced." (PMID 33526980, 2021). "The possibility of hyperglycaemia, itself, acting as a spur for proteolysis has been explored in normal subjects with the use of combined insulin and somatostatin administration." (PMID 34220705, 2021). "(c) It potentiates glucose-dependent insulin secretion from the β-cells and inhibits glucagon secretion from the α-cells in the presence of hyperglycemia (increases insulin/glucagon ratio)." (PMID 33419065, 2021). "Subsequently, similar findings demonstrated that apocynin significantly reduced hyperglycemia, hyperinsulinemia, and dyslipidemia by improving insulin sensitivity in HFD fed mice as well." (PMID 33668280, 2021). "Maternal hyperglycemia stimulates the synthesis of insulin in the fetus, which is an important growth factor." (PMID 34579011, 2021). "T2D is usually caused by the association of deficiency in insulin release by β cells located in the pancreas with the inefficiency of tissues in responding to insulin, which results in impaired glucose metabolism and hyperglycemia." (PMID 34858333, 2021). "The main causes of functional changes in the male reproductive system in T2DM are postprandial hyperglycemia, insulin and leptin resistance, inflammation, elevated production of the reactive oxygen and nitrogen species, oxidative stress and lipotoxicity." (PMID 35008624, 2021). "In our study, 22% of the neonates required insulin therapy for idiopathic hyperglycemia (45% among <28 weeks)." (PMID 34447729, 2021).